RN7SKP179 (RN7SK pseudogene 179)
Gene: Miscellaneous RNA gene on chromosome 2 (190,553,264 to 190,553,480, reverse strand). Ensembl gene ENSG00000251935.
Homologues: Orthologues: chimpanzee 7SK (100% identical), guinea pig 7SK (51% identical), mouse Gm56184 (45% identical). Paralogues in human: RN7SKP208 (62% identical), RN7SKP153 (62% identical), RN7SKP163 (62% identical), RN7SKP221 (62% identical), RN7SKP296 (62% identical), 7SK (61% identical), RN7SKP111 (61% identical), RN7SKP131 (61% identical), RN7SKP224 (61% identical), RN7SKP63 (61% identical), RN7SKP69 (61% identical), RN7SKP137 (61% identical), and 284 more.